POLG (DNA polymerase gamma, catalytic subunit)
Diseases named in the same sentence as POLG in open-access papers (continued):
Sharing a sentence is not in itself a finding about the gene and the disease.
Ataxia (continued). "Spinocerebellar ataxias due to repeat expansions and pathogenic variants in 188 ataxia genes, including POLG but not POLG2, were excluded prior to exome sequencing in the index patient and her affected brother." (PMID 37085601, 2024). "Similarly, the ARCA Registry has enabled the natural history of POLG-related ataxia to be documented through longitudinal SARA and INAS assessments." (PMID 34248822, 2021). "Interestingly, ataxia was the major feature (90%) for POLG patients with onset between 12 and 40 years, and the second feature (58%) after ocular myopathy in older subjects." (PMID 33802970, 2021). "Notably, only 12 studies reported data from muscle biopsies of patients with POLG-related ataxia." (PMID 41245005, 2025). "Large cerebellar lesions resembling infarcts are rarer but may be seen in POLG-1-related ataxia." (PMID 41245005, 2025). "Abnormalities of the nervous system, including neurodevelopmental abnormality (HP:0012759), ataxia (HP:0001251), seizure (HP:0001250), peripheral neuropathy (HP:0009830) etc., were present in 44% of the families reported, and the top five contributing genes were POLG, SPG7, MFN2, FXN and C19ORF12." (PMID 39423307, 2025). "Moreover, some disorders were assigned as many as three phenotypic prefixes while some other disorders that are among the most prevalent causes of recessive ataxia, such as POLG, were not assigned an ataxia prefix." (PMID 31267374, 2019). "Moreover, the electrophysiological finding of a demyelinating component of the sensorimotor peripheral neuropathy will help to distinguish ARSACS from other common recessive ataxias like Friedreich’s ataxia, POLG or AOA2, where neuropathy is almost exclusively of axonal type." (PMID 23497566, 2013). "Genetic analysis of the POLG gene to exclude SANDO syndrome, screening for spinocerebellar ataxias, metabolic evaluation for adrenoleukodystrophy, antibody panels for nodopathies, serum protein electrophoresis, and antineuronal antibody panels were all negative." (PMID 41363019, 2025). "The phenotypic spectrum of POLG-related mitochondrial disease includes progressive external ophthalmoplegia (PEO), sensory and cerebellar ataxia, encephalopathy, neuropathy, focal and generalised epilepsy, dysarthria, distal myopathy, Parkinsonism, liver disease and premature ovarian failure." (PMID 26735972, 2016). "An important issue is the lack of clinical characterization of patients’ symptoms in many cases; particularly, the type of ataxia was often not determined, referring solely to “gait imbalance” or “clumsiness”, and not all common accompanying symptoms of POLG-related disease were reported." (PMID 41245005, 2025). "However, POLG rs2072267 was also investigated in Parkinson’s disease, ataxia, and colorectal cancer, but no significant results were reported." (PMID 36833361, 2023). "We propose that POLG-related mitochondrial disease should be a differential diagnosis in cases of de novo status epilepticus, particularly with other clinical features such as ataxia and external ophthalmoplegia, irrespective of age." (PMID 28815208, 2017).
Parkinsonism (54 papers, 2009 to 2025). Characteristic neurologic anomaly resulting from degeneration of dopamine-generating cells in the substantia nigra, a region of the midbrain, characterized clinically by shaking, rigidity, slowness of movement and difficulty with walking and gait. "In a study involving adult patients with mitochondrial movement disorders, 12% had parkinsonism related to POLG mutations, whereas POLG-related parkinsonism generally has an early onset between the third and fourth decade of life." (PMID 40362688, 2025). "Parkinsonism is the most frequently observed extrapyramidal movement disorder in patients with POLG mutations and has been associated with both dominant and recessive mutations." (PMID 37648940, 2023). "POLG gene should be considered in the differential diagnosis of parkinsonisms, and POLG mutations should be tested especially in families with autosomal dominant transmission." (PMID 33802970, 2021). "We present an 80-year-old male with drug-induced Parkinsonism and tardive akathisia with an incidental POLG mutation." (PMID 34179544, 2021). "Secondary mtDNA rearrangements due to nuclear gene (mostly POLG) mutations and mtDNA genetic abnormalities can, sometime, cause parkinsonism." (PMID 33802970, 2021). "Parkinsonism has been associated with both autosomal dominant and recessive POLG mutations and has an early age of onset, typically around the 3rd–4th decade." (PMID 34179544, 2021). "POLG mutations have been linked to degeneration of the nigrostriatal system similar to PD with concomitant, though variable, parkinsonism." (PMID 34056672, 2021). "Several patients with POLG mutations and multiple mtDNA deletions also present with early onset parkinsonism." (PMID 31143191, 2019). "In comparison in ageing muscle 80% of mtDNA deletions were found to have repeats, which is similar to findings in the substantia nigra in ageing, Parkinson’s disease and a patient with a POLG mutation." (PMID 31147703, 2019). "POLG is the most common inherited mutation in patients with parkinsonism and mitochondrial diseases." (PMID 29751692, 2018). "Instead, Parkinsonism associated with mitochondrial diseases is largely restricted to mutations affecting the mtDNA maintenance genes POLG and TWINKLE (encoding the mtDNA polymerase and helicase, respectively), but is inconsistently observed." (PMID 29616350, 2018). "Extrapyramidal features, including dystonia, akathisia (motor restlessness), Parkinsonism and tardive dyskinesia, have been described in patients harbouring POLG mutations." (PMID 27287935, 2017). "Although mutations in POLG are the most common to be associated with parkinsonism in mitochondrial disease patients, there are reports of point mutations associated with these symptoms." (PMID 24503004, 2014). "Mutations in POLG should be looked for in cases of Parkinsonism, especially when multisystem neurological involvement is found." (PMID 24099403, 2013). "Here we present the case of a 48-year-old woman carrying a homozygous mutation (p.A899T) in mitochondrial polymerase gamma (POLG) and manifesting with a complex neurological phenotype including Dopamine-agonist responsive Parkinsonism." (PMID 24099403, 2013). "Parkinsonism can be associated with both dominant and recessive POLG mutations." (PMID 40362688, 2025). "POLG is a nuclear-encoded mtDNA polymerase; it has been observed that defective POLG in humans leads to increased mtDNA deletions and premature aging hallmarks, such as parkinsonism and early menopause." (PMID 38425363, 2024). "The most common movement disorder found in association with POLG mutation is Parkinsonism." (PMID 34179544, 2021). "Parkinsonism is the most common movement disorder reported in association with POLG mutations." (PMID 34179544, 2021). "Parkinsonism is the most common movement disorder associated with POLG mutation." (PMID 34179544, 2021).
Parkinsonism (continued). "Interestingly, primary mitochondrial disorders occasionally present with parkinsonism, e.g., in patients harboring mutations in the nuclear POLG gene." (PMID 34828446, 2021). "Parkinsonism is the most common movement disorder associated with POLG mutations." (PMID 34179544, 2021). "In addition, mutations in POLG have been implicated in Parkinsonism related symptoms and potentially accelerated aging." (PMID 32138667, 2020). "The POLG pol domain mutation may lead to parkinsonism as it aggravates oxidative stress in the dopaminergic neurons." (PMID 30941926, 2019). "Similar to POLG, mutations in other nuclear genes, like twinkle, a mtDNA helicase required for mtDNA replication and stability, lead to accumulation of mtDNA deletions and have been found to be associated with parkinsonism." (PMID 29707191, 2018). "Therefore, POLG defects should be regarded as a secondary genetic cause of Parkinson’s disease, with affected patients presenting earlier onset and variable response to levodopa." (PMID 26251896, 2015). "If the POLG mutation was responsible for the parkinsonism then one might expect most POLG patients to exhibit this phenotype, many patients with POLG mutations have cell loss within the SN, but this is not always associated with PD like symptoms." (PMID 24503004, 2014). "In previous years, co-existence of Parkinsonism and POLG mutations has been described, suggesting that mitochondrial dysfunction might play a role in the pathogenesis of PD." (PMID 24099403, 2013). "Importantly, breakpoint analysis revealed that the types of ΔmtDNA that have clonally expanded in nigra neurons from PD patients and age-matched controls are similar to those from a patient with POLG mutations who had parkinsonism." (PMID 22188897, 2011). "Furthermore, gene defects of the mtDNA polymerase γ (POLG) result in the accumulation of ΔmtDNA and can cause parkinsonism." (PMID 22188897, 2011). "POLG is a proof reading enzyme for mtDNA which was shown in association to Parkinson's disease." (PMID 19290059, 2009). "This unique role in mitochondrial genome maintenance distinguishes POLG from other PD-associated genes involved in mitochondrial dynamics, highlighting a primary contribution to parkinsonism via mtDNA instability rather than altered mitophagy or respiration." (PMID 40362688, 2025). "However, there are reports on the association between Parkinsonism and POLG mutations." (PMID 29751692, 2018). "Our report aimed to identify POLG involvement in a sample of 33 patients presenting with neurodegenerative disorders, including PD, some atypical parkinsonisms, and dementia of different types." (PMID 37189790, 2023). "Remarkably, variants in POLG, TWNK, and TFAM are not only known as a monogenic cause of primary mitochondrial disorders (occasionally presenting with parkinsonism) but can also increase the risk for PD." (PMID 34828446, 2021). "Parkinsonism accompanying progressive external ophthalmoplegia (PEO), ptosis and neuropathy was also found to segregate with POLG mutations in a few families." (PMID 26251896, 2015). "As for POLG mutations, PEO1 defects have been found to segregate with Parkinsonism and additional syndromic features in dominant PEO families." (PMID 26251896, 2015). "Few reports also described premature ovarian failure with Parkinsonism and PEO in women harboring POLG variants." (PMID 26251896, 2015). "POLG-related parkinsonism has an earlier onset than PD typically ~ 40 years but even earlier." (PMID 37648940, 2023). "We also summarize all reported cases of POLG-related Parkinsonism, along with a literature review." (PMID 34179544, 2021). "In addition, H3K27 hyperacetylation was observed in genes associated with more complex forms of parkinsonism and/or vulnerability to PD-related pathology such as FBOX7 and POLG." (PMID 33947435, 2021). "We performed a literature search to summarize all reported cases of POLG-related Parkinsonism." (PMID 34179544, 2021).
Parkinsonism (continued). "A literature search revealed 55 cases of “POLG-related Parkinsonism” that met our criteria." (PMID 34179544, 2021). "For example, mutations in the POLG gene that encodes POLγ are linked to various diseases, including progressive external ophthalmoplegia (PEO), mitochondrial recessive ataxia syndrome (MIRAS), Parkinsonism, and Alpers–Huttenlocher syndrome." (PMID 34071708, 2021). "The extent to which POLG variants play a role in the development of Parkinson’s disease is still not established." (PMID 34179544, 2021). "Further studies are required to explain why most patients with biallelic C10orf2 mutations do not exhibit parkinsonism despite demonstrating severe substantia nigra neuronal loss (which also occurs with biallelic POLG mutations)." (PMID 32847958, 2020). "The mechanistic basis of the exceptionally variable nervous system defects of POLG—from epilepsy to cognitive decline, ataxia, psychiatric symptoms, and parkinsonism—is unknown." (PMID 29109127, 2018). "Lewy body pathology is also seen in elderly individuals with no Parkinson's disease symptoms and recently we found evidence of Lewy body pathology in a patient with POLG mutations, but with no corresponding extrapyramidal features." (PMID 24503004, 2014). "Here we report on a patient carrying a homozygous mutation in POLG and manifesting with a complex neurological phenotype fitting the clinical diagnosis of SANDO (sensory ataxic neuropathy, dysarthria, and cophthalmoparesis) syndrome including Dopamine-agonist responsive Parkinsonism." (PMID 24099403, 2013). "Intriguingly, for some specific mutations in genes related to other phenotypes (e.g. hereditary dementias, SCAs, POLG-related ataxias, SPG7) parkinsonism may even represent the core clinical manifestation at the onset, making molecular diagnosis difficult." (PMID 37648940, 2023). "Sever nigral degeneration without parkinsonism has been observed in disorders with cerebellar involvement, including SCA2 and SCA3, mitochondrial encephalopathy with POLG mutations, and MSA-C." (PMID 33785066, 2021). "A normal DaT scan ruled out Parkinson’s disease, and molecular analysis for POLG was positive (E1143G)." (PMID 34179544, 2021).
epilepsy (40 papers, 2010 to 2025). A brain disorder characterized by episodes of abnormally increased neuronal discharge resulting in transient episodes of sensory or motor neurological dysfunction, or psychic dysfunction. "Studies have reported that POLG mutations are frequently encountered in epilepsy patients, with 128 pathogenic POLG variants being associated with seizures." (PMID 40565516, 2025). "It has been shown that in 84% of epilepsy patients, at least one of the pathogenic variants in the POLG gene, including p.Ala467Thr, p.Trp748Ser, and p.Gly848Ser, is present." (PMID 40565516, 2025). "Only two patients (P9 and P10, both with POLG variants) were diagnosed with epilepsy before their first SLE." (PMID 39666093, 2024). "For instance, patients with POLG-related epilepsy are at a higher risk of morbidity and mortality due to seizures and their case should be discussed promptly with a mitochondrial disease specialist." (PMID 39677188, 2024). "In POLG patients also earlier disease onset, previous diagnosis of epilepsy, and compound heterozygous variants are associated with worse prognosis." (PMID 39666093, 2024). "Altogether 128 pathogenic POLG variants have been associated with epilepsy, W748S, A467T and G848S being the most common variants." (PMID 39666093, 2024). "Cortical reactive astrocytes in patients with adult-onset mitochondrial disease, including patients with POLG-related epilepsy, demonstrate mitochondrial OXPHOS protein deficiencies and decreased abundance of the ATP-dependent enzyme glutamine synthetase." (PMID 37259148, 2023). "Epilepsy occurs frequently in patients with POLG mutations and a total of 128 POLG mutations have been linked with seizures." (PMID 28837072, 2017). "Epilepsy is common in polymerase gamma (POLG) related disease and is associated with high morbidity and mortality." (PMID 28837072, 2017). "Of interest, in the same patient, we also excluded genetic conditions potentially leading to focal brain lesions and seizure disorder, including POLG mutations." (PMID 25033936, 2014). "This study is significant for understanding and treating patients with epilepsy, because POLG gene mutations have a high prevalence and are hence a potentially important cause of severe intractable epilepsy." (PMID 23448099, 2013). "It has clearly been shown that POLG encoding the catalytic α-subunit of mitochondrial DNA polymerase gamma, is one of the genes causing epilepsy." (PMID 23448099, 2013). "In conclusion,POLG mutations have a high prevalence and are hence a potentially important cause of severe intractable epilepsy." (PMID 23448099, 2013). "In a recent publication on 19 patients with the two most common POLG mutations, p.W748S or A467T, 13 (76%) had epilepsy, which was an early and defining feature of the disease with a poor prognosis." (PMID 23448099, 2013). "Myopathy, encephalopathy, lactate acidosis, and stroke-like episodes (MELAS), myoclonus epilepsy and ragged red fibers (MERRF), and polymerase gamma (POLG)-related disease are the three most common mitochondrial encephalomyopathies and are closely associated with epilepsy." (PMID 33363507, 2020). "Our results are consistent with previous observations of a predisposition for occipital lobe involvement in POLG-related epilepsy, in terms of clinical, neurophysiologic and radiologic findings; however, the precise explanation of such preferential involvement remains unknow." (PMID 33113942, 2020). "This review included 195 cases affected by epilepsy due to POLG-1 mutations." (PMID 33113942, 2020). "Whether the brain atrophy was part of the syndrome has not been definitely established, but brain atrophy has been found in 28% of patients with POLG-associated epilepsy." (PMID 32042919, 2020). "Moreover, biallelic POLG mutations are associated with several epilepsy phenotypes." (PMID 41245005, 2025).